LAG3 (lymphocyte activating 3)
Description:
[Lymphocyte activation gene 3 protein]: Inhibitory receptor on antigen activated T-cells. Delivers inhibitory signals upon binding to ligands, such as MHC class II, its main ligand present at the surface of antigen-presenting cells (APCs), and FGL1, which is secreted by hepatocytes and certain types of tumor cells. Ligand-binding initiates a signaling that inhibits the T-cell receptor (TCR) in the immunological synapse, preventing T-cell activation. Mechanistically, ligand-binding promotes (1) ubiquitination of the KIEELE motif, unleashing the RRFSALE motif from the membrane and (2) leading to the formation of condensates with the TCR component CD3E, thereby disrupting the association between CD3E and LCK and preventing TCR activation. May inhibit antigen-specific T-cell activation in synergy with PDCD1/PD-1 (By similarity). Negatively regulates the proliferation, activation, effector function and homeostasis of both CD8(+) and CD4(+) T-cells. Also mediates immune tolerance: constitutively expressed on a subset of regulatory T-cells (Tregs) and contributes to their suppressive function (By similarity). Also acts as a negative regulator of plasmacytoid dendritic cell (pDCs) activation (By similarity). The LAG3-mediated inhibitory pathway is exploited by tumors to attenuate anti-tumor immunity and escape destruction by the immune system, thereby facilitating tumor survival. The blockage of the LAG3- and PDCD1-mediated pathways results in the reversal of the exhausted T-cell phenotype and the normalization of the anti-tumor response, providing a rationale for cancer immunotherapy. [Secreted lymphocyte activation gene 3 protein]: May function as a ligand for MHC class II (MHC-II) on antigen-presenting cells (APC), promoting APC activation/maturation and driving Th1 immune response.
Synonyms: CD223
Tractability: Antibody: an approved drug acts on it; UniProt places it where antibodies can reach, with high confidence; its Gene Ontology location is reachable by antibodies, with high confidence; UniProt predicts a signal peptide or a membrane-spanning region. Other modalities: a drug acting on it is in phase 2 or 3 trials.
Gene: Protein-coding gene on chromosome 12 (6,772,360 to 6,778,455, forward strand). Ensembl gene ENSG00000089692.
Subcellular location: Cell membrane (Lymphocyte activation gene 3 protein); Secreted (Secreted lymphocyte activation gene 3 protein)
Pathways (Reactome):
Immune System: MHC class II antigen presentation
Gene Ontology:
Molecular function: MHC class II protein binding; protein binding; transmembrane signaling receptor activity; antigen binding
Biological process: negative regulation of T cell activation; negative regulation of T cell mediated immune response to tumor cell; negative regulation of T cell receptor signaling pathway; cell surface receptor signaling pathway; negative regulation of regulatory T cell differentiation; plasmacytoid dendritic cell activation; regulation of immune response
Cellular component: plasma membrane; cell surface; extracellular region; external side of plasma membrane
Genetic constraint (gnomAD): Loss-of-function variants: 32 observed, 48.15 expected, observed/expected ratio (o/e) 0.66, 90% interval 0.5 to 0.89. The upper end of that interval is the gene's LOEUF score, 0.89, which puts it in group 3 of 6, group 1 being the genes least tolerant of losing a copy. Missense variants: 693 observed, 637.73 expected, observed/expected ratio (o/e) 1.09, 90% interval 1.02 to 1.16. Synonymous variants: 320 observed, 275.19 expected, observed/expected ratio (o/e) 1.16, 90% interval 1.06 to 1.28.
Homologues: Orthologues: chimpanzee LAG3 (99% identical), macaque LAG3 (93% identical), dog LAG3 (78% identical), rabbit LAG3 (77% identical), pig LAG3 (74% identical), guinea pig LAG3 (72% identical), mouse Lag3 (69% identical), rat Lag3 (67% identical), zebrafish zmp:0000000936 (13% identical). Paralogues in human: IL1RL1 (15% identical), IL18R1 (13% identical), IL18RAP (13% identical), IL1RL2 (13% identical), IL1RAPL1 (13% identical), IL1R1 (13% identical), IL1R2 (12% identical), IL1RAP (11% identical), IL1RAPL2 (11% identical), SIGIRR (9% identical).
Diseases named in the same sentence as LAG3 in open-access papers:
LAG3 is named in the same sentence as 354 diseases in open-access papers, as found by Europe PMC text mining. Sharing a sentence is not in itself a finding about the gene and the disease. The quoted sentences say what the papers report.
melanoma (432 papers, 2011 to 2026). A malignant, usually aggressive tumor composed of atypical, neoplastic melanocytes. "Another analysis of the TCGA cohort had linked LAG3 promoter hypomethylation to better overall survival in melanoma patients." (PMID 40307913, 2025). "Existing literature indicates that high LAG3 expression is associated with poorer prognosis in malignant melanoma and pancreatic cancer." (PMID 40411616, 2025). "Noteworthy among these findings include a missense variant in LAG3 (P67T), an inhibitory immune receptor for which inhibitors have been recently approved as immunotherapy in advanced melanoma." (PMID 39041034, 2024). "On the other hand, higher MHC II expression allows binding to lymphocyte activation gene-3 (LAG3) on melanoma-associated T cells, ultimately ensuring melanoma cell survival in vitro." (PMID 38419052, 2024). "LAG-3 expression in peripheral blood lymphocytes is also associated with resistance to ICI therapies in patients with melanoma and urothelial carcinoma." (PMID 37928556, 2023). "Lastly, an ongoing seven-year trial with ClinicalTrials.gov ID: NCT05608291 is comparing fianlimab as anti-LAG-3 plus cemiplimab (anti-PD-1) to pembrolizumab as adjuvant therapy in completely resected high-risk melanoma patients." (PMID 37627153, 2023). "In conclusion, our study investigating LAG-3 expression in baseline melanoma specimens reveals the strong association between higher LAG-3 expression and response to combination anti-LAG-3 and anti-PD-1 immunotherapy." (PMID 37808404, 2023). "RTP4 has also been reported that it is significantly associated with immune cell infiltration and immune checkpoint encoding genes (PDCD1, TIM-3, and LAG3) in melanoma." (PMID 37152371, 2023). "This review reports the dermatologic side effects associated with LAG‐3 inhibitors used in the treatment of melanomas." (PMID 38047262, 2023). "LAG-3, along with its ligands Galectin-3 and HLA-II, was found to be particularly expressed in melanoma lesions with inflamed T-cell phenotypes such as high-risk uveal melanoma, where Gal-3/LAG-3 interplay restricts T-cell-mediated responses." (PMID 37345056, 2023). "Relatlimab in combination with nivolumab has shown efficacy in melanoma patients with LAG3 expression in at least 1% of tumor-associated immune cells, demonstrating an ORR of 18% (n = 33)." (PMID 35345849, 2022). "Confirming the importance of checkpoint receptors on Vδ2 T-cells a recent study documents increased proportions of Vδ2 T-cells expressing LAG3 in melanoma patients, a finding which was associated with earlier relapse and shorter overall survival." (PMID 36713444, 2022). "This study aims to investigate the association of LAG3 DNA methylation with gene expression, clinicopathological parameters, molecular and immune correlates, and outcome in melanoma." (PMID 32861198, 2020). "We validated the association of LAG3 methylation with mRNA expression in vitro in the melanoma cell line A375 treated with the hypomethylating agent 5-azacytidine and stimulated with interferon-γ." (PMID 32861198, 2020). "High co-expression of CD163 and LAG-3 was associated with poor clinicopathological indexes of melanoma and worse survival compared to the high expression of the single markers." (PMID 32756500, 2020). "LAG-3 and its ligands, Galectin-3 and MHC-II, exhibit high expression levels in melanoma lesions, particularly within inflamed T-cell phenotypes such as high-risk uveal melanoma, where the interaction between Galectin-3 and LAG-3 attenuates T-cell-mediated responses." (PMID 39743998, 2024). "The constitutive expression of LAG-3 in immune cells is associated with this state of exhaustion and has been linked to a weakened antitumor immune response in a wide variety of tumors, such as melanoma, Hodgkin’s lymphoma, CLL, and colorectal cancer." (PMID 39425148, 2024).
melanoma (continued). "In melanoma, higher LAG3 mRNA expression is linked to the hypomethylation of beads 1 through 13, and the hypomethylation of the LAG3 promoter and the CTCF binding site may enhance immune cell infiltration." (PMID 38041068, 2023). "Lymphocyte activation gene 3 (LAG-3, also known as CD223) is an IC belonging to the immunoglobulin superfamily (IgSF), strictly associated with human tumor prognosis, mostly negative, but also to positive outcomes, like in gastric carcinoma and melanoma." (PMID 37626933, 2023). "Furthermore, our results indicated that elevated expression of LAG3 was associated with a better prognosis in melanoma (P < 0.0001) and thyroid cancer (P = 0.0149)." (PMID 38062416, 2023). "In melanoma, LAG3 mRNA expression is associated with LAG3 promoter methylation." (PMID 35111155, 2021). "In melanoma, the hypomethylation of beads 1 to 13 is associated with higher LAG3 mRNA expression." (PMID 35111155, 2021). "In addition, PD-L1 overexpression in melanoma tumors has been associated with increased LAG-3 expression." (PMID 30941125, 2019). "The targeting of LAG-3 in combination with other checkpoint therapies has been a focus of ongoing clinical trials – exemplified by a recent study that associated LAG-3 expression on peripheral CD8+ T cells with a poorer efficacy of checkpoint blockade in melanoma and urothelial carcinoma patients." (PMID 35265944, 2022). "Indeed, in extracranial tumors, LAG-3 expression in melanoma was shown to be associated with better prognosis and response to immune checkpoint inhibitors; however, further translational data from trials investigating LAG-3-blocking agents in solid tumors are needed." (PMID 33651248, 2021). "Although its role is still not fully understood, it can be speculated that LAG-3 expression on TAMs contributes to their tumor-promoting function, as suggested by the association of co-expression of CD163 and LAG-3 with poor clinicopathological indexes in melanoma and metastatic ovarian cancer." (PMID 33374804, 2020). "Collectively, these data show that in melanoma, although γδ T cells appear capable of producing cytokines, induction of LAG-3 and CTLA-4 in response to TCR and IL-15 is impaired." (PMID 41310392, 2026). "In the prospective clinical trial (RELATIVITY‐020), anti‐LAG‐3 combined with anti‐PD‐1 was considered as a safety strategy for advanced melanoma." (PMID 41492362, 2026). "In the Phase II/III, double‐blind, randomized RELATIVITY‐047 study (NCT03470922), the researchers evaluated relatlimab (LAG‐3 blocking antibody) combined with nivolumab compared with nivolumab alone to patients with previously untreated advanced melanoma." (PMID 41492362, 2026). "In patients receiving anti-PD-1 and anti-LAG-3 for melanoma, enhanced responses were noted in patients with increased baseline T cell clonality linked to CMV46." (PMID 40269332, 2025). "Simultaneous blockade of lymphocyte activation gene-3 (LAG-3) and programmed-death-1 (PD-1) pathways enhance anti-tumor activity in patients with melanoma." (PMID 41282765, 2025). "Serum levels of LAG-3 in patients with melanoma increase after anti-PD-1 monotherapy and subsequently decrease following dual blockade of LAG-3 and PD-1." (PMID 39751894, 2025). "Translational data across trials showed lower circulating LAG-3+ T cells in the adjuvant setting (RELATIVITY-098) versus advanced melanoma (RELATIVITY-047), where LAG-3+ T cells were enriched in tumor versus blood." (PMID 41109920, 2025). "The overexpression of LAG-3 on γδ T cells was previously reported in regard to numerous cancers and during chronic inflammation, for e.g., melanoma or Plasmodium vivax infection." (PMID 40136700, 2025). "The co‐expression of LAG‐3 with PD‐1/PD‐L1 has been documented in multiple cancers, including melanoma, lymphoma, germ cell tumors,[4b] breast cancers, and lung cancers among others." (PMID 39513410, 2025).
melanoma (continued). "In patients with advanced melanoma, there was a higher percentage of LAG-3+ and LAG-3+PD-1+ CD8 T cells in tumor samples than in blood samples." (PMID 41109920, 2025). "The authors also tested LAG3 methylation as a predictive biomarker in 118 immunotherapy-treated melanoma patients and demonstrated a better progression-free survival in patients with hypomethylated melanomas." (PMID 40307913, 2025). "In summary, these findings suggest that iEV-150 promotes ferroptosis in melanoma, inhibits tumor proliferation, and enhances tumor cell sensitivity to anti-PD-1 and anti-LAG3 immunotherapy." (PMID 40860143, 2025). "The combination of LAG-3 inhibition with PD-1 blockade (e.g., relatlimab plus nivolumab) has demonstrated superior clinical efficacy in melanoma, sustaining T-cell activity against tumour cells while impeding immune escape mechanisms." (PMID 40895685, 2025). "For example, the concurrent blockade of PD-1 and lymphocyte-activation gene 3 (LAG-3) has enhanced the cytotoxic function of CD8+T cells in melanoma patients, improving therapeutic outcomes." (PMID 41315319, 2025). "LAG-3 negatively regulates T-cell proliferation and function and is frequently co-expressed with PD-1 on exhausted T cells in melanoma." (PMID 40647451, 2025). "This is the case with the combination of anti-PD-1 (nivolumab) with anti-LAG-3 (relatlimab) in the first-line treatment of advanced melanoma." (PMID 39859576, 2025). "Clinical trials combining two immune checkpoints (LAG3 and PD-1) for previously untreated metastatic or unresectable melanomas have demonstrated the feasibility of anti-LAG3 treatment." (PMID 40411616, 2025). "Compared with the control and iEV-NC groups, melanoma-bearing mice treated with iEV-150 showed enhanced antitumor responses when receiving the same dose of anti-PD-1 or anti-LAG3 antibodies, as reflected by reduced tumor size and weight." (PMID 40860143, 2025). "Despite significant advances in targeted (BRAFi + MEKi) and immune (anti-PD1/PD-L1, anti-CTLA4, and anti-LAG3) therapies, treatment options for NRASmut melanoma remain limited." (PMID 41035005, 2025). "Combining anti-TIGIT and anti-LAG-3 with conventional anti-PD-1/anti-PD-L1 therapies has been shown to improve median survival in non-small cell lung carcinoma and melanoma." (PMID 40647508, 2025). "LAG-3 is a T-cell inhibitory receptor upregulated during PD-1 therapy; relatlimab (anti-LAG-3) combined with nivolumab showed success in melanoma and is now in HNSCC trials." (PMID 41374963, 2025). "Most notably, the triple combination of iEV-150, anti-PD-1, and anti-LAG3 had the strongest antitumor effects on melanoma-bearing mice." (PMID 40860143, 2025). "These immune checkpoint inhibitors (CPIs), particularly ones targeting PD-1, CTLA4 and LAG3, have revolutionized the treatment of many cancers and have been especially effective in the treatment of melanoma." (PMID 41325134, 2025). "Clinical trials of advanced melanoma have shown that the combining nivolumab with relatlimab, the first approved LAG‐3 mAb, can improve PFS and OS compared with nivolumab alone, and nivolumab plus relatlimab is safer than nivolumab plus ipilimumab." (PMID 40415479, 2025). "Metastatic melanoma can be treated with anti-PD-1 monotherapy or in combination with anti-CTLA-4 or anti-Lag3." (PMID 40148586, 2025). "In recent years, anti-PD-1 combined with anti-LAG3 therapies have been tested and applied clinically for the treatment of malignant melanoma." (PMID 40411616, 2025). "In clinical trials, relatlimab (anti-LAG-3 monoclonal antibody) combined with nivolumab (anti-PD-1) achieved FDA approval for advanced melanoma (Phase III RELATIVITY-047 trial), demonstrating superior progression-free survival (PFS: 10.1 vs. 4.6 months)." (PMID 40948781, 2025). "Recent survival analyses have demonstrated tumor-specific effects of LAG3 expression on overall survival across various malignancies, including esophageal carcinoma, breast cancer, and malignant melanoma." (PMID 40411616, 2025).